CLEC4M (C-type lectin domain family 4 member M)
Description:
Probable pathogen-recognition receptor involved in peripheral immune surveillance in liver. May mediate the endocytosis of pathogens which are subsequently degraded in lysosomal compartments. Is a receptor for ICAM3, probably by binding to mannose-like carbohydrates. (Microbial infection) Acts as an attachment receptor for Ebolavirus. (Microbial infection) Acts as an attachment receptor for Hepatitis C virus. (Microbial infection) Acts as an attachment receptor for HIV-1. (Microbial infection) Acts as an attachment receptor for Human coronavirus 229E. (Microbial infection) Acts as an attachment receptor for Human cytomegalovirus/HHV-5. (Microbial infection) Acts as an attachment receptor for Influenzavirus. (Microbial infection) Acts as an attachment receptor for SARS-CoV. (Microbial infection) Acts as an attachment receptor for West-nile virus. (Microbial infection) Acts as an attachment receptor for Japanese encephalitis virus. (Microbial infection) Acts as an attachment receptor for Marburg virus glycoprotein. (Microbial infection) Recognition of M.bovis by dendritic cells may occur partially via this molecule.
Synonyms: DC-SIGNR; DC-SIGN2; L-SIGN; CD299; CD209L; CD209L1; HP10347; LSIGN; DCSIGNR
Tractability: Small molecule: a structure with a bound ligand is known; it has a high-quality binding pocket. Antibody: UniProt places it where antibodies can reach, with high confidence; its Gene Ontology location is reachable by antibodies, with high confidence; UniProt predicts a signal peptide or a membrane-spanning region. PROTAC: a small molecule that binds it is known.
Target class: Membrane receptor
Gene: Protein-coding gene on chromosome 19 (7,763,153 to 7,769,606, forward strand). Ensembl gene ENSG00000104938.
Subcellular location: Cell membrane (Isoform 1); Cell membrane (Isoform 2); Cell membrane (Isoform 3); Secreted (Isoform 5); Secreted (Isoform 6); Secreted (Isoform 7); Secreted (Isoform 10)
Pathways (Reactome):
Disease: RSV-host interactions
Gene Ontology:
Molecular function: calcium-dependent protein binding; protein binding; virus receptor activity; carbohydrate binding; D-mannose binding; ICAM-3 receptor activity; pattern recognition receptor activity; peptide antigen binding; signaling receptor activity; virion binding
Biological process: receptor-mediated virion attachment to host cell; symbiont entry into host cell; antigen processing and presentation; cell-cell recognition; immune response; intracellular signal transduction; intracellular transport of virus; leukocyte cell-cell adhesion; peptide antigen transport; receptor-mediated endocytosis of virus by host cell; viral genome replication; virion attachment to host cell
Cellular component: cytoplasm; external side of plasma membrane; membrane; plasma membrane; extracellular region; host cell
Genetic constraint (gnomAD): Loss-of-function variants: 23 observed, 37.51 expected, observed/expected ratio (o/e) 0.61, 90% interval 0.44 to 0.87. The upper end of that interval is the gene's LOEUF score, 0.87, which puts it in group 3 of 6, group 1 being the genes least tolerant of losing a copy. Missense variants: 346 observed, 413.92 expected, observed/expected ratio (o/e) 0.84, 90% interval 0.76 to 0.91. Synonymous variants: 148 observed, 163 expected, observed/expected ratio (o/e) 0.91, 90% interval 0.79 to 1.04.
Homologues: Orthologues: chimpanzee CLEC4M (96% identical), dog CD209 (25% identical), pig CD209 (24% identical), rat Cd209fl1 (23% identical), mouse Cd209f (22% identical), rat Cd209f (21% identical), mouse Cd209g (19% identical), zebrafish asgr1a (15% identical), tropical clawed frog clec4m (15% identical), Drosophila melanogaster tfc (14% identical), tropical clawed frog clec4e (13% identical), tropical clawed frog asgr1 (12% identical), and 16 more. Paralogues in human: CD209 (72% identical), CLEC4C (17% identical), CLEC17A (17% identical), CLEC4E (16% identical), CLEC4G (16% identical), CLEC10A (16% identical), CLEC4D (16% identical), CLEC4A (15% identical), ASGR1 (15% identical), CLEC6A (15% identical), ASGR2 (15% identical), FCER2 (15% identical), and 2 more.
Diseases named in the same sentence as CLEC4M in open-access papers:
CLEC4M is named in the same sentence as 44 diseases in open-access papers, as found by Europe PMC text mining. Sharing a sentence is not in itself a finding about the gene and the disease. The quoted sentences say what the papers report.
viral infection (16 papers, 2009 to 2025). "Therefore, ACE2, TMPRSS2, and CLEC4M could support viral infection through the space of Disse." (PMID 38074511, 2024).
COVID-19 (12 papers, 2020 to 2024). A disease caused by infection with severe acute respiratory syndrome coronavirus 2. "Out of 22 eligible articles that investigated candidate genes (2 as associated with COVID-19), the top-ranked genes in the number of studies were ACE2, CLEC4M (L-SIGN), MBL, MxA (n = 3), ACE, CD209, FCER2, OAS-1, TLR4, TNF-α (n = 2)." (PMID 32917282, 2020). "Although we highlighted hACE2 as a binding partner of SARS-CoV-2, a number of studies presented different docking partners of the human host to SARS-CoV-2 infections, such as NRP1, L-SIGN(CLEC4M), DC-SIGN(CD209), and CD147(BSG)." (PMID 35816517, 2022). "Furthermore, changes in the expression of the ACE2, TMPRSS2, CLEC4M and DPP4 genes, observed in TC, also occur in COVID-19." (PMID 39767735, 2024).
colon carcinoma (10 papers, 2013 to 2025). "CLEC4M has been identified as one of the genes that differentially expressed in patient colon cancer hepatic metastasis specimens and its xenograft." (PMID 23658834, 2013). "Subsequent studies confirmed that CLEC4M could promote colon cancer liver metastasis." (PMID 31772670, 2019). "Knockdown of CLEC4M expression remarkably inhibited the migration of NSCLC cells, which was in line with the observation that CLEC4M promotes the invasion of colon cancer cells." (PMID 31772670, 2019). "Additionally, lymph node-specific ICAM-3 grabbing non-integrin (L-SIGN/DC-SIGNR/CLEC4M) and LSECtin have been implicated in adhesion and migration of colon cancer cell metastasis to the liver." (PMID 32982772, 2020).
lung cancer (5 papers, 2019 to 2022). A malignant neoplasm involving the lung. "This study mainly focused on the association of CLEC4M with clinical prognosis and the particular role of CLEC4M in cisplatin resistance in lung cancer patients." (PMID 31772670, 2019). "In conclusion, to the best of our knowledge, this is the first report to demonstrate that higher expression of CLEC4M is associated with poor clinical prognosis in lung cancer patients and enhances the resistance of NSCLC cells to cisplatin." (PMID 31772670, 2019). "Moreover, a high CLEC4M expression level is implicated in cisplatin resistance and correlates with a poor prognosis in patients with lung cancer (non–small cell lung cancer)." (PMID 36496984, 2022). "CLEC4M was successfully knocked down in the human lung cancer cell lines A549 and H1299; we also observed a remarkable increase in CLEC4M expression at both the mRNA and protein levels, which demonstrated that CLECM was successfully overexpressed." (PMID 31772670, 2019). "To determine whether CLEC4M influences the sensitivity of lung cancer cell lines to cisplatin, we investigated the impact of CLEC4M on cell proliferation." (PMID 31772670, 2019). "Our results found that CLEC4M was correlated with poor prognosis in patients with lung cancer." (PMID 31772670, 2019). "Based on these observations, one intriguing issue is whether and how CLEC4M contributes to the aetiology of lung cancer and impacts cisplatin sensitivity." (PMID 31772670, 2019). "The biological effects of CLEC4M in lung cancer remain unclear." (PMID 31772670, 2019). "CLEC4M, SLC10A2 and FGF4 have been found to be involved in lung cancer progression and the regulation of treatment resistance." (PMID 33005178, 2020).
liver cancer (4 papers, 2017 to 2022). An epithelial or non-epithelial malignant neoplasm that arises from the liver. "In more detail, a significant reduction of TMPRSS2 and CLEC4M in kidney and liver cancers, as well as a significant increase of DPP4 in thyroid cancer, was highlighted." (PMID 32970391, 2020). "HCC patients exhibiting CLEC4M overexpression have a better OS, and CLEC4M overexpression inhibits the proliferation of liver cancer cells and promotes their apoptotic death." (PMID 33228611, 2020).
hepatocellular carcinoma (3 papers, 2020 to 2024). A malignant tumor that arises from hepatocytes. "For example, CLEC4M expression is downregulated in hepatocellular carcinoma and this downregulation is believed to promote inflammation and metastasis of HCC." (PMID 33247676, 2020). "CLEC4M has been identified as prognostic liver tissue biomarker of hepatocellular carcinoma." (PMID 38335183, 2024). "Initially, a pair of key genes, namely CLEC4G and CLEC4M were found with significant difference between tumors and controls, when retrieved a public dataset (GSE104310) of hepatocellular carcinoma." (PMID 33123293, 2020).
colorectal cancer (1 paper, 2019). A primary or metastatic malignant neoplasm that affects the colon or rectum. "Despite minimal data regarding the role of this gene in cancer, a recent study demonstrated that CLEC4M actually supports adherence, invasion, and liver metastasis in colorectal cancer with minimal difference upon cell proliferation." (PMID 30857282, 2019).
Crohn disease (1 paper, 2020). A gastrointestinal disorder characterized by chronic inflammation involving all layers of the intestinal wall, noncaseating granulomas affecting the intestinal wall and regional lymph nodes, and transmural fibrosis. "Ileal CLEC4M that encodes CD209L was revealed to have significantly decreased expression in Crohn's disease (CD), suggesting possible protective implications against SARS-CoV-2 in CD patients." (PMID 32714386, 2020).
ovary cancers (1 paper, 2020). "Similarly, CLEC4M shows high expression levels in liver and ovary normal tissues (1st and 4th in rank) and has differential expression in liver and ovary cancers." (PMID 32970391, 2020).
Parkinson disease (1 paper, 2025). A progressive degenerative disorder of the central nervous system characterized by loss of dopamine producing neurons in the substantia nigra and the presence of Lewy bodies in the substantia nigra and locus coeruleus. "In this study, we identified seven hub genes—PI3, TMSB15A, CLEC4M, CD4, SEMA6A, PLXND1, and AVP—that collectively drive Parkinson’s disease progression through synergistic mechanisms." (PMID 41329689, 2025).
steatosis (1 paper, 2024). Increased lipid within the cytoplasm of cells. "The expression of TMPRSS2 remained unchanged in MASLD, whereas the MERS-CoV receptor dipeptidyl peptidase 4 (DPP4) and the SARS-CoV-2 coreceptor CLEC4M were lower in steatosis and steatohepatitis, with respect to controls." (PMID 38074511, 2024).
thyroid cancer (1 paper, 2020). "The AUC > 0.80 shown by TMPRSS2, CLEC4M and DPP4 suggests that these genes may act as effective molecular markers for kidney, liver and thyroid cancers." (PMID 32970391, 2020).
type 1 VWD (1 paper, 2018). "The promoter and all exons and introns of CLEC4M except exon 4 were screened for variants in 106 individuals from unrelated type 1 VWD families by Sanger sequencing." (PMID 29389944, 2018). "The overall goal of the study was to investigate whether genetic variants in CLEC4M are associated with type 1 VWD in the Swedish population looking at both common and rare variants." (PMID 29389944, 2018). "Thus, CLEC4M was suggested to be causally involved in the development of type 1 VWD." (PMID 29389944, 2018). "CLEC4M also binds to VWF and variants in this gene contribute to the variation in the VWF level observed both in normal individuals and in type 1 VWD patients." (PMID 29389944, 2018). "The rs868875 variant in CLEC4M showed association with both VWF level and activity in 364 type 1 VWD patients from the Netherlands." (PMID 29389944, 2018). "In order to screen for CLEC4M variants, the CLEC4M gene region was re-sequenced and the polymorphic neck region was genotyped in 106 type 1 VWD patients from unrelated type 1 VWD families." (PMID 29389944, 2018). "It has also been shown that the CLEC4M protein binds to and internalizes VWF, and variants in CLEC4M contribute to the variability of VWF plasma levels in type 1 VWD patients." (PMID 29389944, 2018). "In conclusion, heterozygous VNTR genotypes 57 and 67 of CLEC4M were highly enriched and are the most likely mechanism through which CLEC4M contributes to disease in the Swedish type 1 VWD population." (PMID 29389944, 2018). "The present study aimed to screen comprehensively for genetic variation in the CLEC4M gene in individuals from 106 unrelated type 1 VWD families by re-sequencing the gene region (excluding exon 4) and genotyping the polymorphic neck region (exon 4) of the gene." (PMID 29389944, 2018).
infection (58 papers, 2008 to 2025). The state of being infected such as from the introduction of a foreign agent such as serum, vaccine, antigenic substance or organism. "Previously genetic variation in the neck region of CLEC4M has been associated, for example, with susceptibility to infection by HIV and SARS." (PMID 29389944, 2018). "SARS-CoV utilizes ACE2, CD209, CLEC4G, and CLEC4M for its infection to host." (PMID 33330620, 2020). "Till now, many researchers had reported that susceptibilities to infection SARS-CoV may associated with HLA, MXA, OAS-1 and CLEC4M gene polymorphisms, yet these results were variable in different populations." (PMID 18312678, 2008). "Till now, many researchers have reported that susceptibility to infection SARS-CoV may associate with HLA, MXA, OAS-1 and CLEC4M gene polymorphisms, yet the results are variable in different populations." (PMID 18312678, 2008). "For this reason, SARS-CoV-2 Spike, similar to HIV, binds CLEC4M (or CD299) and DC-SIGNR (or CD209), facilitating the infection of the immune system." (PMID 37375496, 2023). "Analysis of the connection between SARS-CoV-2 interactome revealed direct interaction of the virus glycoprotein S with 3 of the 11 virus-infection related proteins identified as incomplete in the ACE2 network (ACE2, CLEC4M, and TMPRSS2)." (PMID 33233425, 2020). "Several reports also link neck length variation to variation in infection rates for viruses such as HIV and SARS-CoV both on the allelic and genotypic levels; other reports indicate that the HIV transfection efficiency is due to the number of CLEC4M proteins on the cell surface." (PMID 29389944, 2018). "For example, C-type lectins such as DC-specific intercellular adhesion molecule 3 (ICAM3)-grabbing non-integrin (DC-SIGN; CD209) and liver/lymph node-SIGN (L-SIGN; CLEC4M) are sufficient to enable MARV glycoprotein-mediated infection." (PMID 40333058, 2025).
tumor (12 papers, 2014 to 2025). "Numerous studies have indicated that C-type lectin domain family 4 member M (CLEC4M) is associated with the progression of various tumor types." (PMID 36496984, 2022). "High expression of CLEC4M is associated with microvascular invasion, increased tumor volume, loss of tumor encapsulation, decreased tumor differentiation, predicted poor relapse-free survival, and overall survival (OS)." (PMID 33974527, 2021). "However, the expression of CLEC4A, CLEC4D, CLEC4E, CLEC4J (FCER2), CLEC4K (CD207), CLEC4G, CLEC4H1, CLEC4M, and CLEC4H2 decreased with tumor progression." (PMID 34409028, 2021).
cancer (10 papers, 2014 to 2024). A tumor composed of atypical neoplastic, often pleomorphic cells that invade other tissues. "Here, the expression of five genes, known to encode coronavirus receptors/interactors (ACE2, TMPRSS2, CLEC4M, DPP4 and TMPRSS11D), was investigated in normal and cancer tissues, and their molecular relationships with clinical comorbidities were investigated." (PMID 32970391, 2020). "Recently, the clinical significance of CLEC4M in cancers has been investigated." (PMID 31772670, 2019). "Specifically, ACE2, TMPRSS2, CLEC4M, DPP4 and transmembrane protease serine 11D (TMPRSS11D) were analyzed by assessing their RNA expression levels in different body districts and in different cancer types." (PMID 32970391, 2020).
infectious disease (4 papers, 2009 to 2018). A disorder directly resulting from the presence and activity of a microbial, viral, or parasitic agent in humans. "Earlier work involving CLEC4M and its relation to infectious disease has generated much debate regarding reported associations." (PMID 29389944, 2018). "In particular, a highly polymorphic variable number tandem repeat (VNTR) at the neck-region of CLEC4M had been associated with genetic predisposition to some infectious diseases." (PMID 22279577, 2012).
CLEC4M also shares sentences with these, for which no sentence is quoted: dengue (6 papers); SARS-CoV infection (5); HIV-1 infection (4); coagulopathy (3); breast carcinoma (2); Dengue hemorrhagic fever (2); gastric cancer (2); metastasis (2); respiratory infection (2); ZIKV Infection (2); acute lymphoblastic leukemia (1); cholangiocarcinoma (1); coronary artery disease (1); diabetes (1); emphysema (1); endothelial dysfunction (1); epilepsy (1); fibrosis (1); influenza (1); invasive breast carcinoma (1); lentivirus infection (1); malignant follicular lymphoma (1); myeloma (1); non-Hodgkin lymphoma (1); thrombosis (1); type 1 von Willebrand disease (1); uterus cancers (1).